LEP (leptin)
Diseases named in the same sentence as LEP in open-access papers (continued):
Sharing a sentence is not in itself a finding about the gene and the disease.
Hyperinsulinemia (continued). "Of relevance, acute injection of leptin-neutralizing antibodies has been shown to induce hyperinsulinemia in mice." (PMID 29795184, 2018). "Serum leptin and insulin levels were comparable between the 2 cohorts at 8 weeks of age, but thereafter, Sel1LPOMC mice developed hyperleptinemia and hyperinsulinemia." (PMID 29457782, 2018). "Production of leptin increases along with increased body fat, with visceral fat mass inducing and aggravating IR, while hyperinsulinemia stimulates the production of leptin." (PMID 29412382, 2017). "In our previous studies we also demonstrated hyperinsulinemia and high leptin serum levels indicating leptin resistance as observed in patients with CP." (PMID 27512604, 2016). "Hyperinsulinemia was present in the majority of patients, and leptin values were very low in all patients." (PMID 26985241, 2016). "The vast majority of obese patients present high concentrations of leptin that are increased depending on the degree of adiposity and hyperinsulinemia, which is referred nowadays as leptin resistance." (PMID 27766104, 2016). "On the one hand, it led to the abnormal transport through the blood–brain barrier of leptin and insulin, leading to decreased levels of insulin and leptin in the CNS despite of the existence of hyperinsulinemia and hyperleptinemia." (PMID 27867820, 2016). "In contrast, NAFLD rats fed with the HFD showed hyperinsulinemia and increased leptin levels compared to the lean controls." (PMID 26924554, 2016). "Correlation of fetal insulin with fetal leptin levels suggests that fetal hyperinsulinemia, by stimulating white adipose tissue growth, the main leptin source, leads to higher leptin production in fetal adipose tissue." (PMID 25258707, 2014). "Our data raise several questions in targeting leptin signaling as a treatment for cancer: how to restrict antagonizing actions to the periphery; how to prevent adverse effects such as hyperinsulinemia; how to improve bioavailability to cancer." (PMID 24587106, 2014). "The intraperitoneal injection of 2.17-mAlb at high-dose (100 μg/mouse, daily) resulted in weight gain, hyperphagia, increased adiposity, hyperleptinemia, and hyperinsulinemia indicating efficient blockade of leptin signaling in CNS." (PMID 24587106, 2014). "Experimental animal research and studies in human beings have shown that hyperinsulinemia increased plasma leptin concentrations." (PMID 25368558, 2014). "The complex pathophysiology of hyperinsulinemia, i.e. increased serum level of insulin-like growth factor-1 (IGF-1) and leptin and its association with the risk of PMBC has been evaluated previously and discussed extensively." (PMID 24340245, 2013). "In the obese state, an increase in adipose tissue mass leads to increased secretion of insulin and leptin into the circulation resulting in the development of hyperinsulinemia and hyperleptinemia, respectively." (PMID 23590862, 2013). "In the obese state, an increase in adipose tissue mass leads to increased secretion of insulin and leptin into the circulation, often resulting in the development of hyperinsulinemia and hyperleptinemia, respectively." (PMID 21904565, 2012). "Leptin resistance in pancreatic beta cells can disrupt leptin suppression of insulin via the adipo-insular axis and promote hyperinsulinemia." (PMID 22458475, 2012). "Changes in metabolic parameters occurred as early as 6-weeks in DIO mice as evidenced by hyperinsulinemia, increased leptin levels and modestly increased levels of pro-inflammatory mediators, including CCL2 and IL-6, in the serum and in the EF pad." (PMID 20445733, 2010). "Elevated fasting plasma TG levels have also been described in the offspring of 30% caloric restricted dams throughout pregnancy, and this has been found in conjunction with hyperinsulinemia and leptin resistance." (PMID 20796266, 2010).
Hyperinsulinemia (continued). "The results indicate that leptin infusion can attenuate hepatic steatosis and hyperinsulinemia through the reduction of hepatic triglyceride synthesis and the improvement of insulin sensitivity in diet-induced lipodystrophy model mice." (PMID 18348717, 2008). "Additionally, it presents intense hyperphagia, suppression of blood leptin levels, hypothyroidism, hypogonadism, and hyperinsulinemia, among others." (PMID 41013830, 2025). "In addition, the KATP channels in the dorsal motor nucleus of the vagal nerve, pancreatic β-cells, and adipocytes are activated, reducing hyperinsulinemia and body fat, directly or indirectly leading to improved insulin and leptin resistance and satiety." (PMID 40136445, 2025). "Notably, a bidirectional regulatory relationship exists between leptin and insulin: insulin serves as a key regulator of leptin production, and chronic hyperinsulinemia sustains elevated circulating leptin levels." (PMID 41476920, 2025). "Interestingly, levels of several hormonal peptides related to hyperinsulinemia, such as insulin, leptin, pancreatic peptide (PP), peptide YY (PYY), and gastric inhibitory polypeptide (GIP), were significantly upregulated." (PMID 39851552, 2025). "Although still debated, chronic hyperinsulinemia promotes leptin resistance." (PMID 40950761, 2025). "In the presence of prolonged hyperinsulinemia, plasma leptin concentrations increase." (PMID 37691744, 2023). "Prolonged hyperinsulinemia results in an increase in circulating levels of leptin." (PMID 37660067, 2023). "Previous studies have demonstrated that leptin deficiency (ob/ob mice) significantly increases lipogenic flux independent of hyperphagia and hyperinsulinemia." (PMID 38036455, 2023). "In diabetic rats, both basal and glucose-stimulated (120 min after glucose loading) levels of insulin and leptin also increased, indicating the development of hyperinsulinemia, hyperleptinemia, and resistance to insulin and leptin, which are characteristic features of DM2." (PMID 37108424, 2023). "These include hyperinsulinemia, elevated leptin, chronic inflammation, oxidative stress, activation of HIF-1α and cytokines, DNA methylation, dysfunctional visceral adipose tissue secretome, adipokine and exosome miRNA release and alterations in the sex hormone metabolism." (PMID 37047163, 2023). "The mice display hyperinsulinemia, hyperleptinemia, leptin resistance, and hyperphagia." (PMID 36702632, 2023). "Although leptin exhibits anorexigenic effects and promotes the extinction of fear memories, hyperinsulinemia in PTSD patients results in leptin resistance, leading to increased appetite, decreased memory performance, and impaired synaptic plasticity in the hippocampus." (PMID 37374323, 2023). "Second, hyperinsulinemia and high levels of leptin have carcinogenic effects." (PMID 37467012, 2023). "Thus, an antagonizing effect of leptin on hepatic insulin signalling was suggested under hyperinsulinemia conditions." (PMID 35896788, 2022). "Leptin treatment may reduce food intake, fat mass, hyperinsulinemia, and hyperlipidemia in humans, and restores normal pubertal development, endocrine, and immune function." (PMID 36232301, 2022). "Furthermore, a systematic literature review provided evidence for a higher frequency of metabolic abnormalities in LEP wt/- than in wt/wt subjects, including hypercholesterinemia, hyperinsulinemia, and hypertriglyceridemia." (PMID 35677722, 2022). "Prolonged hyperinsulinemia leads to an increase in leptin’s plasma concentration, while short-term hyperinsulinemia does not cause such a change." (PMID 34084149, 2021).
Hyperinsulinemia (continued). "Leptin, adiponectin, and hyperinsulinemia are also probably involved." (PMID 34574647, 2021). "The overproduction of leptin by the adipose tissue could result from: (a) hyperinsulinemia; (b) chronic inflammation; and (c) significant lipid disturbances in CKD patients." (PMID 33925217, 2021). "We reasoned that the higher levels of serum Manf in obese mice and humans may be the result of its compensatory up-regulation, like the hyperinsulinemia and high level of leptin in obese subjects." (PMID 33856409, 2021). "The mechanisms of HO could be various, including hyperphagia, impaired energy expenditure and thermoregulation, vagally mediated hyperinsulinemia, and defective hypothalamic leptin signal transduction." (PMID 34603197, 2021). "An increased leptin level and hyperinsulinemia were associated with weight gain in pubertal girls, but not in boys, with T1D45." (PMID 34272437, 2021). "Fetal hyperinsulinemia during critical periods may induce leptin resistance (leptin is a hormone that reduces food intake and increases energy expenditure)." (PMID 32098435, 2020). "Hyperinsulinemia and low plasma leptin levels are typically present." (PMID 29704234, 2019). "On the other hand, the increased circulating irisin may represent an “irisin resistance” state, similar to the insulin and leptin resistance that results in hyperinsulinemia and hyperleptinemia observed in obese individuals." (PMID 31015797, 2019). "Leptin secretion from circulation acts as a signal in the brain of patients with hyperinsulinemia." (PMID 29189992, 2018). "There is also evidence that the insulin receptor signaling pathway interferes with leptin signaling, suggesting that hyperinsulinemia may contribute to leptin resistance." (PMID 27943202, 2017). "In the heart, leptin or insulin may be considered either metabolic or growth factors for the heart and hyperinsulinemia and hyperleptinemia are documented in SL rodents at several stages of development." (PMID 27465434, 2016). "The high leptin in hyperinsulinemia of PCOS women may be a secondary consequence of insulin-stimulated leptin synthesis." (PMID 26180527, 2015). "The presence of hyperinsulinemia in fasted male fructose-fed progeny along with hyperleptinemia could also indicate leptin resistance at the level of pancreatic islets." (PMID 25763281, 2015). "Other explanations put forward for the low ghrelin levels observed in obese subjects include the action of leptin reducing ghrelin release, as a response to constant, high food intake, a common pattern among obese individuals, or in patients with hyperinsulinemia." (PMID 25892993, 2015). "Lustig reviewed that chronic hyperinsulinemia may prevent DA clearance from the NAc and leptin signalling, leading to leptin resistance and increased food intake." (PMID 25296886, 2015). "Hypothalamic dysfunction can lead to hyperinsulinemia and leptin resistance." (PMID 26371051, 2015). "High circulating levels of leptin in db/db mice may therefore play a role in the development of hyperinsulinemia, and studies using these mice may potentially be confounded by this effect." (PMID 24809394, 2014). "It was suggested that resistance to leptin in β-cells might prevent the inhibitory effect of leptin on insulin secretion resulting in hyperinsulinemia, which might exhaust pancreatic β-cells leading to development of T2DM." (PMID 23853613, 2013). "Placental production of leptin might be responsible for hyperinsulinemia in the offspring of DM mother." (PMID 20336197, 2009). "Although insulin and leptin bind to separate receptors in the neurons of the VMH and VTA, they share the same signaling cascade, called insulin receptor substrate-2 (IRS2)/phosphatidyl inositol-3-kinase (PI3K) and thus hyperinsulinemia may block leptin signaling." (PMID 40950761, 2025). "Elevated leptin levels stimulated by increased TSH may lead to hyperinsulinemia and IR." (PMID 41040505, 2025).
Hyperinsulinemia (continued). "In addition, leptin therapy may affect insulin receptor substrates, such as insulin-2, directly or indirectly by reducing endogenous hyperinsulinemia." (PMID 38957655, 2024). "Additionally, it has been suggested that menstrual cycle disorders in obese women may be related to disorders of estrogen metabolism, changes in the concentration of SHBG, hyperinsulinemia, and changes in leptin levels." (PMID 38769497, 2024). "First, adipose tissue can lead to hyperinsulinism, which may increase serum leptin." (PMID 39062887, 2024). "Improvements in chronic peripancreatic adipose tissue inflammation, leptin, hyperinsulinemia, T2DM, KRAS activation, IGF and intestinal microbiome after dietary intervention and bariatric surgery may explain the decreased development of pancreatic ductal adenocarcinoma after bariatric surgery." (PMID 37047163, 2023). "However, a number of scientists suggest that the steroid-induced rise in leptin levels are not fully dependent on the hyperinsulinemia caused by GCs." (PMID 36699046, 2022). "This may be explained by reduced mobility, higher fall frequency, inflammatory stress, inadequate levels of leptin, adiponectin, and ghrelin, hypoestrogenism and hyperinsulinism, storage of vitamin D in adipose tissue, and elevated levels of parathyroid hormone." (PMID 36294434, 2022). "GH treatment presented similar effects regarding ALT and sarcopenia reduction; however, it was associated with hepatomegaly, hyperinsulinemia, the reduction of serum levels of leptin and adiponectin and no significant steatosis reduction in histology assessment." (PMID 29724029, 2018). "Thus, hyperinsulinemia inobese women may happen due to the effects of reduced adiponectin levels andincreased leptin and resistin in circulation." (PMID 28050960, 2016). "It is the upregulation of proinflammatory mediators, that is, TNF-α and leptin, and the downregulation of anti-inflammatory molecules, that is, adiponectin, that lead to the development of chronic inflammatory state and contribute to the hyperinsulinemia in GDM." (PMID 25202741, 2014). "Additionally, previous studies have reported a phenomenon that normal growth without growth hormone might be associated with hyperinsulinemia, hyperprolactinemia, elevated leptin levels, and growth hormone variants." (PMID 38828392, 2024). "Offspring of mothers fed a high-fat diet were found to have hyperinsulinemia, hyperglycemia, and increased LPL and leptin gene expressions." (PMID 37899888, 2023). "Leptin impairs glucose transporter-4 (GLUT-4) translocation in skeletal muscle and induces hyperinsulinemia, which results in coactivation of the SNS." (PMID 34073163, 2021). "Furthermore, considering that leptin is secreted not only by adipose tissue but also by the gastric mucosa in response to food intake and insulin, hyperleptinemia could be regarded as a result of an increased production of gastric leptin elicited by hyperinsulinemia." (PMID 32092909, 2020). "One of the mechanisms of leptin overexpression in breast tumors seems to involve HIF-1α, a component of HIF transcriptional factor that can be upregulated by hypoxia and hyperinsulinemia." (PMID 31380268, 2019). "Moreover, an association of leptin levels with hyperinsulinemia and hyperandrogenism in women with NC-CAH was not established with conclusion that potential relation of leptin with hyperinsulinemia and reproduction in NC-CAH patients need further investigation." (PMID 31632355, 2019). "This raises the question of what the role of leptin is in EMS, particularly in animals with post-prandial hyperinsulinemia." (PMID 31339945, 2019). "Leptin signaling, specifically in the hypothalamic ARC, is a major feeding-independent regulator of glucose homeostasis, improving hyperinsulinemia, and normalizing blood glucose levels." (PMID 31500090, 2019).
Hyperinsulinemia (continued). "Pooled regression analysis indicated that reductions in hyperinsulinemia, gauged as the insulin response during OGTT, leptin and PRA, and enhancement of BRS were independently associated with sympathoinhibition within the cohort." (PMID 27857694, 2016). "Along with hyperinsulinemia, we also observed increased leptin levels in NAFLD, which is likely due to leptin resistance." (PMID 26924554, 2016). "Leptin reduces hypothalamic NPY levels and increases sympathetic activity with hyperinsulinemia, resulting in appetite suppression." (PMID 22518191, 2012). "External supplementation of recombinant murine leptin ameliorate CLA-induced hepatic steatosis and hyperinsulinemia by decreasing hepatic lipogenesis and increasing insulin sensitivity respectively." (PMID 21869929, 2012). "Offspring weaned to HC deviated from maternal HFHS improved hyperlipidemia (TC and LDL) and hyperinsulinemia, but not leptin levels." (PMID 35736495, 2022). "A further difference is that induced hyperinsulinemia led to an increase in leptin levels in females, but not males." (PMID 35637895, 2022). "D lutheri supplementation partially prevented hyperinsulinemia observed in the HF group (−50%) and markedly decreased the plasma leptin level (−67%), whereas the glycemia was not restored." (PMID 35807489, 2022). "Although the detailed link is not clear, mechanisms including hyperinsulinemia, chronic inflammation and changes in circulating fat factors (including leptin and adiponectin) had been proposed." (PMID 35831811, 2022). "Besides marrow adipose tissue and adipokines, such as leptin and adiponectin, other probable mechanisms involved in CGL high BMD are muscle hypertrophy, hyperinsulinemia, low sexual hormone binding globulin (SHBG), and osteoarthritic degeneration." (PMID 34574647, 2021). "Butyrate corrected hyperinsulinemia, lowered plasma leptin levels, and attenuated adipose tissue inflammation, without affecting gut permeability or microbiota composition." (PMID 34944770, 2021). "The use of a KATP channel activator which is capable of penetrating the DVC has the potential to recapitulate the effects of leptin, insulin and α-MSH, with the likely result being reductions in hyperinsulinemia, reductions in hepatic gluconeogenesis, reductions in appetite and improved satiety." (PMID 32326226, 2020). "In addition to basal hyperinsulinemia, mice fed HFD for 15 weeks showed significantly increased leptin and PAI-1 levels, together with lower circulating concentrations of adiponectin, ghrelin and glucagon." (PMID 30382123, 2018). "The observed hyperinsulinemia and hyperleptinemia were highly correlated with HFCD-induced weight gain, recapitulating conditions in most overweight or obese individuals who have at least some degree of insulin and leptin resistance." (PMID 29651002, 2018). "The HF mice displayed the significant hyperinsulinemia and hyperleptinemia (p < 0.001, p < 0.001, respectively), and TRR1-, TRR2-, TRR3-, Feno-, and Metf-treated mice significantly lowered levels of blood insulin and leptin." (PMID 29099085, 2017). "Fructose-fed male rats were resistant to the hepatic effects of leptin, whereas fructose-fed females had no signs of leptin resistance but had hyperinsulinemia and altered glucose tolerance test." (PMID 25763281, 2015). "We previously generated mice lacking leptin signaling in β-cells by using the Cre-loxP strategy and showed that these animals develop increased body weight and adiposity, hyperinsulinemia, impaired glucose-stimulated insulin secretion and insulin resistance." (PMID 23936486, 2013). "Leptin levels in PWS relate to the amount of adipose tissue in the same way as in obese non-PWS individuals, whereas the prevalence of impaired glucose intolerance, hyperinsulinemia, and type 2 diabetes seems to be lower compared to that in obese non-PWS controls." (PMID 40136445, 2025).